CXCL12 (C-X-C motif chemokine ligand 12)
Diseases named in the same sentence as CXCL12 in open-access papers (continued):
Sharing a sentence is not in itself a finding about the gene and the disease.
cancer (continued). "The interaction between CXCL12 secreted by CAFs and CXCR4 expressed in cancer cells is also accountable for the direct growth effects elicited by activated stromal cells." (PMID 29240722, 2017). "Several lines of evidence have conclusively suggested that expression of chemokine CXCL12 and its specific receptor CXCR4 on cancer cells promote metastasis." (PMID 28658303, 2017). "There are reports shown that fibroblasts involve in the cross-talk of cancer cells and fibroblasts by secreting CCL2, CCL5, CXCL1, CXCL6, CXCL12, IL6, CXCL16 and others." (PMID 28465475, 2017). "An important target population for CXCL12-mediated recruitment and signaling are CXCR4+ cancer stem cells, which are mostly found in the invasive front and are essential for metastasis." (PMID 28423491, 2017). "According to the divergence of CXCR4 expression in different cancers, extensive analyses of CXCR4 expression levels and functional studies will be necessary to understand the precise roles of CXCR4/CXCL12 signaling in different cancer types." (PMID 29020982, 2017). "To investigate the roles of miR-125b involved in the CXCL12/CXCR4 axis induced EMT, we examined morphologic changes and expression of molecules related to EMT in cancer cells transfected with miR-125b mimics." (PMID 28176874, 2017). "Actin polymerization, or cytoskeletal reorganization, is a surrogate marker of cancer cell migration and metastatic potential, induced by the interaction of CXCR4 with CXCL12." (PMID 28526063, 2017). "Dysfunction of the CXCL12/CXCR4 axis contributes to several human pathologies, including cancer and inflammatory diseases." (PMID 28410420, 2017). "Expression profiles of CXCL12 and CXCR4 are closely related to biological behaviors of cancer cells and the outcome of patients with GC." (PMID 28544785, 2017). "Collectively, these data suggested that senescent cells work as a ‘storming party' in the collective invasion of cancer through SASP, including MMPs and CXCL12/CXCR4 signalling." (PMID 28489070, 2017). "Affecting the CXCL12 signaling axis has potential for significant therapeutic benefit, as CXCR4 is over-expressed in more than 20 human cancers." (PMID 28055968, 2017). "The recruitment of MDSCs into tumor sites is primarily mediated by various cancer cells that produce chemokines, including CCL2, CCL15, CXCL5, and CXCL12." (PMID 28337221, 2017). "AMD3100 is efficient at inhibiting the proliferation, invasion, and migration of GC cells by attenuating not only the downstream signaling of CXCL12/CXCR4 axis but also interactions between TME and cancer cells." (PMID 28544785, 2017). "This is also accompanied by increased expression of CXCL12, CXCL10, as well as markers of cancer progression, including CD44, ZEB1 and vimentin." (PMID 28445977, 2017). "Here, we demonstrated that CXCR4-expressing PTC cells were able to follow CXCL12-expressing senescent thyrocytes, and that CXCL12-expressing senescent thyrocytes effectively attracted CXCR4-expressing cancer cells in the migration assay." (PMID 28489070, 2017). "Above all, these results suggest that ESR1, FOXO1, CXCL12, and GNAO1 are involved in the pathogenesis of carcinoma by affecting cell division, complement activation, and protein activation cascades, which support our findings." (PMID 28302149, 2017). "Another CAF-related mechanism to stimulate angiogenesis is to recruit endothelial progenitor cells (EPCs) into the carcinoma site by secretion of stromal cell-derived factor 1 (SDF-1), also known as C-X-C motif chemokine 12 (CXCL12)." (PMID 29112161, 2017). "The CXCL12/CXCR4 axis has been involved in homing of breast and prostate cancer cells to bone where cancer cells have aberrant expression of CXCR4, the receptor for the CXCL12 chemokine." (PMID 27809841, 2016). "CXCR4 and its specific ligand, stromal-derived factor 1 (SDF-1), also referred to as CXC ligand 12 (CXCL12), together play a crucial role in cancer survival and metastasis." (PMID 27213454, 2016).
cancer (continued). "It has been demonstrated that CXCL12 and CXCR7, another high affinity receptor of CXCL12, except for CXCR4, play pivotal roles in growth, migration, chemotaxis, adhesion and spreading of cancers." (PMID 27542220, 2016). "CXCL12 is the only ligand for CXCR4 (C-X-C motif receptor 4) and acts as autocrine/paracrine growth factor for several cancers, including GB." (PMID 26880981, 2016). "Coupling of stromal cell derived factor 1 (SDF-1a; CXCL12) with its receptor, chemokine (C-X-C motif) receptor (CXCR) 4, plays a critical role in inflammation, as well as in cancer metastasis." (PMID 27270970, 2016). "Studies in microfluidic channels have contributed to the discovery of genes required for cancer cell migration and identification of proteins, such as EGFR or CXCL12, that act as chemoattractants for cancer cells." (PMID 26904541, 2016). "In contrast, expression of miR-31 was significantly up-regulated in cancer, LK, LP and OSMF tissues while expression of one target, CXCL12, was significantly down-regulated in cancer, LK and LP tissues." (PMID 27597234, 2016). "Notably, CXCR4 antagonists can be used as potential drug sensitizers since treatment-induced CXCL12 pathway activation might be involved in acquired drug-resistance mechanisms through several processes, including induction of cancer cell survival, invasion, and stem cell phenotype." (PMID 27307990, 2016). "The chemokine CXCL12 and its corresponding receptor CXCR4 are key players in the development of several cancers." (PMID 27439769, 2016). "Interestingly, gap junction-transferred CXCL12-targeting microRNAs mir127, mir197, mir222, and mir223, can reduce cancer cell proliferation and even induce dormancy that may last for decades, eventually leading to a relapse of the disease due to bone marrow metastasis." (PMID 26798356, 2016). "Although the relationship between CXCL12/CXCR4 expression levels and cell behaviour was described in a variety of malignant tumors, few have assessed this relationship for esophageal cancer." (PMID 27439769, 2016). "CXCL12 (SDF-1α) is a pleiotropic chemokine that participates in the regulation of tissue homeostasis, immune surveillance, inflammatory responses, and cancer development." (PMID 26831924, 2016). "The CXCL12-CXCR4 biological axis consisting of the chemotactic factor CXCL12 and its specific receptor CXCR4 plays an important role in cancer metastasis." (PMID 25866764, 2015). "CXCL12 derived from the peripheral nerves stimulated the invasion and chemotactic migration of CXCR4-positive cancer cells in a paracrine manner, eventually leading to PNI." (PMID 25605248, 2015). "The chemokine CXCL12 (SDF-1) and its receptor CXCR4 were shown to play a key role in regulating the trafficking of cancer cells to sites of metastases." (PMID 25949860, 2015). "Other chemokines such as CXCL12 (Sdf-1) and CCL2 (MCP-1) are secreted by various cancer types and function as autocrine growth factors as well as chemo-attractants for progenitor cells and monocytes/macrophages." (PMID 25743773, 2015). "In addition, the CXCL12 chemokine is constitutively expressed in several other organs including lymph nodes and lungs and can thereby attract not only hematopoietic cells, but also migrating cancer cells that often show high expression levels of the CXCR4 receptor on their cell surface." (PMID 26075720, 2015). "We showed that the peripheral nerve-derived CXCL12 stimulated the invasion and chemotactic migration of CXCR4-positive cancer cells in a paracrine manner, eventually leading to PNI." (PMID 25605248, 2015). "Chemokines, such as stromal-derived factor-1 (SDF-1/CXCL12) secreted by stromal cells, attracts cancer cells by acting its cognate receptor CXCR4." (PMID 25749979, 2015). "CXCL12 and its receptor chemokine (CXC motif) receptor-4 (CXCR4) play a role in migration of hematopoietic stem cells and cancer cells." (PMID 29061949, 2015).
cancer (continued). "CXCL12 primarily binds to CXCR4 and induces intracellular signaling through several divergent pathways, which are involved in progression and metastasis of cancer." (PMID 26078947, 2015). "The accumulating reports have shown that CXCL12 and CXCR4 are overexpressed both in mRNA and protein levels during initiation and progression of cancers." (PMID 26078947, 2015). "A majority of cancer cells and nerve tissues showed distinct immunostaining of CXCR4 and CXCL12 localized to the cytoplasm." (PMID 25605248, 2015). "Proteins responsible for this recurrence include the chemokine receptor CXCR4, which is known to enable CRC metastasis, as well as the cancer-initiating cell marker and peptidase CD26, which terminates activity of its chemokine CXCL12." (PMID 26552750, 2015). "Intriguingly, we found that the PCa cell lines rarely expressed CXCL12, but the majority of cancer cells surrounding or infiltrating in nerves showed distinct immunostaining of CXCR4 and CXCL12." (PMID 25605248, 2015). "Recent studies also show a role of the CXCR4/CXCL12 axis in triggering interaction of cancer cells with microvascular endothelial cells and GBM cancer stem cell transdifferentiation into pericytes." (PMID 24662753, 2014). "In other words, we propose that the opposite action of COUP-TFI on CXCL12 and CXCR4 expression enhances the migration capacity of cancer cells through an increase in sensitivity to exogenous CXCL12 and by limiting the autocrine retention effect of CXCL12." (PMID 24906407, 2014). "CXCR4 selectively binds the CXC chemokine ligand-12 (CXCL12, or SDF-1), which has been found to be important in the tumorigenesis, proliferation, metastasis, and angiogenesis in cancers." (PMID 25471741, 2014). "The CXC chemokine ligand-12 (CXCL12)/CXC chemokine receptor type 4 (CXCR4) axis has been shown to be involved in tumorgenesis, proliferation, and angiogenesis in a variety of cancers including IHCC." (PMID 25471741, 2014). "Stromal cell-derived factor-1 (SDF-1 or CXCL12) and its unique receptor CXCR4 have prominent roles in chemotaxis and metastasis of a diverse number of cancers." (PMID 24941119, 2014). "Directed metastasis of cancer cells is mediated by CXCR4 activation and migration of cancer cells towards CXCL12 expressing organs." (PMID 24658065, 2014). "Both CXCL12 and LPA are key regulators of metastatic processes in several cancers including gastrointestinal cancers." (PMID 25360116, 2014). "The chemokine receptor CXCR4 and its ligand CXCL12, also known as stromal cell-derived factor 1 (SDF-1), are attractive therapeutic targets in the treatment of cancer, as they support migration, proliferation, and survival of cancer cells." (PMID 24966838, 2014). "Meanwhile, CXCL12 and CXCR4 were found to be instrumental for the development and progression of numerous different cancer types of epithelial, haematopoietic or mesenchymal origin." (PMID 24390633, 2014). "The CXCL12/CXCR4-R7 signaling pathway plays a unique role in the regulation of a variety of cell types, including embryonic and cancer cells." (PMID 25484899, 2014). "Herein, our data demonstrate that while receptor expression is increased,CXCL12 expression is significantly diminished in resected PDAC tissue and a battery ofpancreatic cancer cell lines compared to normal pancreata." (PMID 24594697, 2014). "The chemokine network and CXCL12/CXCR4 signaling in particular, as well as EGFR signaling are involved in many aspects of cancer biology, including growth and metastasis." (PMID 24906407, 2014). "In particular, the chemokine (C-X-C motif) ligand 12 (CXCL12) and its receptors, CXCR4 and CXCR7, have been involved in cancer cell proliferation, migration, and invasion." (PMID 25484899, 2014).
cancer (continued). "Because of the critical role that the CXCL12/CXCR4 axis plays in HIV infection and cancer metastasis, it has served as an important target in the development of antitumoral and anti-HIV-1 therapies." (PMID 23987636, 2013). "The chemokine SDF-1/CXCL12 and its canonical receptor CXCR4 are among the most highly studied chemokine/receptor pairs in cancer biology." (PMID 23894550, 2013). "Low CXCL12 and VCAM1 has been related to both cancer progression and improved prognosis in various cancers, but no clear relation to chemo-resistance has been reported." (PMID 22905093, 2012). "In vitro experiments have shown that the directional migration of a range of cancer cells (e.g., ovarian, pancreatic, rhabdomyosarcoma and melanoma) is stimulated by the interaction between CXCR4 and CXCL12." (PMID 22272201, 2012). "One of the major chemokine receptors expressed by cancer cells is CXCR4, the receptor for CXCL12 [stromal cell derived factor-1 (SDF-1)]." (PMID 22433494, 2012). "CAFs secrete high levels of stromal cell-derived factor-1 (SDF-1 or CXCL12), a chemokine that can activate its cognate receptor, CXCR4, which is expressed by many carcinoma cells, and stimulate their proliferation." (PMID 22482058, 2012). "The CXCL12/CXCR4 axis seems involved in angiogenesis, metastasis, and survival; cancer cells expressing CXCR4 migrate and spread along the CXCL12 gradients." (PMID 24212636, 2011). "This is not only an important information about the overallfunction of CXCL12 in the brain, but a potential positive result supporting ongoingefforts toward development of CXCR7-based therapies against cancer and otherpathologies." (PMID 21655198, 2011). "SDF-1 (also known as CXCL12) is a chemokine that plays an important role in immune cell attraction, stem cell homing and cancer metastasis." (PMID 21887363, 2011). "The cancer cells were positive for CXCR4, CXCL12, HER1, HER4 (a chemotactic receptor that responds to HB-EGF), and GM-CSF." (PMID 20946648, 2010). "In particular the imbalanced or aberrant expression of CXCL12 and its receptor CXCR4 strongly affects cancer cell proliferation, recruitment of immunosuppressive cells, neovascularization, and metastasization." (PMID 20049170, 2010). "In conclusion, CXCL12 induced HB-EGF in mononuclear phagocytes and GM-CSF in HeLa and DLD-1 cancer cells, activating or enhancing a GM-CSF/HB-EGF paracrine loop." (PMID 20946648, 2010). "Furthermore, both macrophages and cancer cells were activated upon CXCL12 stimulation in liver biopsies, though we could not conclusively establish whether cancer cells produced their own CXCL12 or merely internalized CXCL12, produced by stromal cells." (PMID 20946648, 2010). "Our results have shown, for the first time, a correlation between hypermethylation of CXCL12 island 4 and ESR1 in patients with histologically advanced cancer, the presence of metastases and death." (PMID 20109227, 2010). "CXCL12 induced mononuclear phagocytes to release HB-EGF, which activated HER1 and triggered anti-apoptotic and proliferative signals in cancer cells." (PMID 20946648, 2010). "HSP27 was also selected due to spectral counts indicative of phosphorylation upon CXCL12 activation of CXCR4, its implications in cancer and protection from apoptosis, and the availability of a phospho-specific antibody at the Ser82 phosphorylation site." (PMID 20661426, 2010). "Among these chemokines and their receptors, the SDF-1 (also referred to as CXCL12)/CXCR4 system has been shown to be involved in both lymph node and distant metastases of several types of cancer." (PMID 19671192, 2009). "Further analysis of cancer-derived stroma has indicated that secreted frizzled-related protein 1 (SFRP1), TGFβ1 and stromal cell-derived factor 1 (SDF-1/CXCL12) are all candidate molecules for inducing tumourigenicity in prostate." (PMID 19040209, 2009).
cancer (continued). "CXCR4 selectively binds the CXC chemokine stromal cell-derived factor 1 (SDF-1, or CXCL12), which has been found to play an important role in tumorigenesis, proliferation, metastasis, and angiogenesis in cancers." (PMID 19002187, 2008). "Cancer cells that express CXCR4 exploit thesame signaling pathway, leading to homing and retention in tissues that arerich in CXCL12." (PMID 18779872, 2008). "As with hematopoietic progenitor cells, release and homing of certain cancer cells require adhesion molecules and Gαi-coupled GPCRs (such as VLA-4, CXCL12/CXCR4)." (PMID 18534032, 2008). "However, no reduction in the ratio between mRNA sequences encoding human CXCR4 and GAPDH was observed in any treatment group suggesting that the absence of immobilised CXCL12 in heparin-treated animals did not select for non-CXCR4-expressing variants of the cancer." (PMID 17726466, 2007). "In particular, binding of CXCL12 on CXCR4-induced β-integrin expression on cancer cells, which was critical to adhesion of cancer cells to VCAM on endothelial cells." (PMID 16819541, 2006). "The chemokine stromal derived factor-1 (SDF-1/CXCL12) and its receptor CXCR4 have been suggested to regulate organ-specific metastasis in various other cancers." (PMID 17083723, 2006). "Human lung fibroblasts, especially when activated into CAFs, secrete cytokines and growth factors (like TGF‐β, IL‐6, PDGF, EGF, HGF, CXCL‐12), ECM proteins, and remodeling enzymes like MMPs and pro‐invasive signals that potentiate cancer stemness and metastasis." (PMID 41537745, 2026). "Notably, CXCL12 shows a positive correlation with MATN3 in most cancers, suggesting a potential link between MATN3 and CXCL12." (PMID 41004439, 2025). "As a chemokine with a crucial function in cancer progression, CXCL12 could bind to CXCR4 and induce multiple signaling pathways related to angiogenesis, cancer progression and metastasis." (PMID 39741182, 2025). "The binding of chemokine stromal cell-derived factor 1 (SDF-1 or CXCL12) to the G-protein coupled receptor CXCR4 activates signaling pathways that lead to the expression of genes involved in EMT, contributing to cancer cell migration, invasion, and metastasis." (PMID 40608162, 2025). "Cancer-associated fibroblasts (CAFs) express and secrete signalling proteins which stimulate cancer cell proliferation, including insulin-like growth factor-1 (IGF-1), hepatocyte growth factor (HGF), stromal-cell-derived factor-1 (CXCL12), and a range of fibroblast growth factors (FGFs)." (PMID 39859271, 2025). "CXCL12, known to be induced by IGF2 and to promote immune suppression, overlapped with IGF1 expression rather than IGF2 in ESCC, suggesting a possible link between interCAFs IGF signaling and immunomodulation in this cancer." (PMID 41228323, 2025). "Recent studies have shown, both in vitro and in vivo, that TA exerts antitumor functions by regulating mROS expression or promoting TRAIL-induced extrinsic apoptosis; it is also an inhibitor of CXCL12 (SDF-1alpha)/CXCR4 and decreases cancer stem cell formation (43, –, 45)." (PMID 39692477, 2025). "Moreover, in IDC paths #1 and #2, marker genes for endothelial cells (VWF and PECAM1), lymphocytes (CD4), macrophages (CD68), chemokines (CXCL12 and CCL5), and chemokine receptors (CXCR4) were expressed highly at the intermediate stages of cancer progression." (PMID 39965034, 2025). "Also, inflammation is involved in cancer proliferation and multiple pro-inflammatory cytokines (e.g., CCL5, CX3CL1, and CXCL12) play a role in cancer." (PMID 40943574, 2025). "Also, CXCL12 acts as a recruiter of CXCR4+ cancer cells, and the physiological expression of CXCL12 in organs such as liver, lungs, and bone marrow promotes metastasis growth in these sites by recruiting CXCR4+ cancer cells." (PMID 40142155, 2025).